HLA-DRB1 (major histocompatibility complex, class II, DR beta 1)
Diseases named in the same sentence as HLA-DRB1 in open-access papers (continued):
Sharing a sentence is not in itself a finding about the gene and the disease.
rheumatoid arthritis (continued). "This residue is reported to lie in the P4 peptide binding pocket of HLA-DRB1 and amino acid changes at this position have previously been associated with autoimmune conditions such as rheumatoid arthritis, type 1 diabetes, and systemic lupus erythematosus." (PMID 35597955, 2022). "The objective of this study is to identify the association of HLA-DRB1 subtypes with rheumatoid arthritis and its severity in Kurdish region." (PMID 35016727, 2022). "For the same reason, we also did not include SNPs from the MHC region, where the human leucocyte antigen HLA-DRB1 has been associated with rheumatoid arthritis (N = 793) and autism (N = 31 families) in separate genetic studies." (PMID 35022383, 2022). "Associations between certain HLA alleles and autoimmune diseases, such as HLA‐DRB1 for rheumatoid arthritis, HLA‐B51 for Behcet's disease, HLA‐B27 for ankylosing spondylitis, HLA‐DQ2/DQ8 for celiac disease, and HLA‐DQB1*06:02 for narcolepsy, are widely known." (PMID 35070271, 2022). "The risk to develop ACPA positive rheumatoid arthritis (RA), the most destructive type of autoimmune arthritis, is carried by HLA-DRB1 alleles containing a 5 amino acid motif: the shared epitope (SE)." (PMID 35774784, 2022). "The ability of the conserved regions to bind to class-II HLA alleles was assessed by docking the lead epitopes in the binding groove of HLA-DRB1, an allele known to predispose individuals to rheumatoid arthritis." (PMID 36422613, 2022). "Rheumatoid arthritis (RA) is associated with HLA-DRB1 genes encoding the shared epitope (SE), a 5-amino acid motive." (PMID 34248985, 2021). "It is important to note that HLA-DRB1*03:01 has also been associated to susceptibility to rheumatoid arthritis, mainly when inherited together with HLA-DRB1*09:01, which is the case of this patient." (PMID 33815474, 2021). "Another SNP, rs660895, maps upstream of HLA-DRB1, and was previously associated with risk of the autoimmune disease Rheumatoid Arthritis." (PMID 31694854, 2020). "HLA-DRB1*03 was published as a risk factor against adalimumab and infliximab in patients suffering from either inflammatory bowel disease or rheumatoid arthritis." (PMID 33143745, 2020). "Our study shows for the first time an association between HLA-DRB1*07:01 and *08:02 alleles and protection against anti-citrullinated protein antibodies-positive rheumatoid arthritis in the Chilean population." (PMID 33327594, 2020). "The SNP rs2395185 and the two cis-mediators, HLA-DRB5 and HLA-DRB1, were reported to be susceptible to ulcerative colitis, and the two HLA genes were also identified in the rheumatoid arthritis GWAS." (PMID 30925861, 2019). "Certain HLA alleles such as HLA-DRB1*0401 show associations with autoimmune diseases, including rheumatoid arthritis and vasculitis." (PMID 31396202, 2019). "An example of this is the “shared epitope” of certain HLA-DRB1 alleles associated with an increased incidence of rheumatoid arthritis." (PMID 31001268, 2019). "The HLA class II region is strongly associated with a wide spectrum of autoimmune disorders, including rheumatoid arthritis, where a specific group of HLA-DRB1 alleles (called the ‘shared epitope’) increases risk two-to-three-fold." (PMID 31731673, 2019). "The RF-positive polyarthritis association at HLA-DRB1 amino acid at position 13 mirrors the association in adult seropositive rheumatoid arthritis (RA)." (PMID 27998952, 2017). "Rheumatoid arthritis (RA) is associated with HLA-DRB1 shared epitope (HLA-DRB1SE) and anti-citrullinated protein autoantibodies (ACPAs)." (PMID 29033912, 2017). "For example, HLA-DRB1*04:01, 04:04, 04:05, 01:01 and 10:10 alleles contribute to rheumatoid arthritis susceptibility." (PMID 26011559, 2015). "In the present study, we found that PADI4 risk allele and HLA-DRB1 shared epitope are independent genetic risks for radiographic progression in Japanese rheumatoid arthritis patients." (PMID 23577190, 2013).
rheumatoid arthritis (continued). "HLA-DRB1, especially the shared epitope (SE), is strongly associated with rheumatoid arthritis (RA)." (PMID 22792215, 2012). "In the Malaysian Epidemiological Investigation of Rheumatoid Arthritis (MyEIRA) case-control study, we recently reported that HLA-DRB1 SE alleles were consistently associated with ACPA-positive RA in three Asian ethnic populations." (PMID 22537824, 2012). "HLA-DRB1*10 was highly associated with rheumatoid arthritis susceptibility in these Asian populations." (PMID 21698259, 2011). "The HLA-DRB1 SE alleles increase the risk of ACPA-positive rheumatoid arthritis in all three Asian populations from Malaysia." (PMID 21698259, 2011). "The purpose of this study was to investigate the association between HLA-DRB1 alleles with susceptibility to rheumatoid arthritis (RA) and production of antibodies against citrullinated proteins (ACPA) and rheumatoid factor (RF)." (PMID 20370905, 2010). "We found that the rs1801275 AA and AG genotypes and the rs1805010 AA genotype were associated with rheumatoid nodules in African-American RA patients who are HLA-DRB1 SE positive and autoantibody positive." (PMID 20444266, 2010). "This study investigated five confirmed rheumatoid arthritis (RA) susceptibility genes/loci (HLA-DRB1, PTPN22, STAT4, OLIG3/TNFAIP3 and TRAF1/C5) for association with susceptibility and severity in an inception cohort." (PMID 20353580, 2010). "The purpose of this study was to examine the diagnostic performance of autoantibodies against citrullinated peptides/proteins (ACPA) and to determine the prevalence of HLA-DRB1 shared epitope alleles (SE) in African patients with rheumatoid arthritis (RA)." (PMID 20196860, 2010). "The genetic contribution to rheumatoid arthritis (RA) susceptibility is undisputed, with replicated associations identified with haplotypes of the HLA-DRB1 locus and SNPs in PTPN22." (PMID 20018087, 2009). "It is applied to the Genetic Analysis Workshop 16 Problem 1 case-control data in which shared-epitope alleles of HLA-DRB1 show very strong association with rheumatoid arthritis." (PMID 20018001, 2009). "The current study applies the MFG test to HLA-DRB1 genotype data from the North American Rheumatoid Arthritis Consortium (NARAC) study to test NIMA as a risk factor for RA." (PMID 18466466, 2007). "Using the GAW 15 Problem 3 simulated data, we show that our novel method can substantially enhance power to detect association with the binary rheumatoid arthritis (RA) phenotype at the HLA-DRB1 locus on chromosome 6." (PMID 18466524, 2007). "Rheumatoid arthritis (RA) is highly associated with HLA-DRB1 *0101, *0102, *0401, *0404, *0405, *0408, *0423, *10, *1001, *1402, and *1406 alleles that encode a shared epitope (SE)." (PMID 18466466, 2007). "The influence of certain alleles of the HLA-DRB1 locus on risk for rheumatoid arthritis has been well established through linkage and association studies." (PMID 18466541, 2007). "The HLA-DRB1 gene was reported to be associated with anticitrullinated protein/peptide autoantibody (ACPA) production in rheumatoid arthritis (RA) patients." (PMID 17328818, 2007). "Several of the induced genes, particularly proinflammatory cytokines IL1β, IL6, and PTGS2 and genes involved in antigen presentation (HLA-DRB1), have been implicated in persistent inflammation in other conditions including atopic dermatitis, psoriasis, and rheumatoid arthritis." (PMID 41333458, 2025). "Susceptibility is strongly shaped by HLA variation, with class II alleles (e.g., HLA-DRB1 shared epitope in rheumatoid arthritis; HLA-DRB1/DQA1/DQB1 in systemic lupus erythematosus and Sjögren’s syndrome) dictating peptide presentation and T cell help to autoreactive B cells." (PMID 41153754, 2025). "Importantly, HLA-DRB1*01:02 has been associated with susceptibility to rheumatoid arthritis, and HLA-DQB1*05:01 with a cluster of severe Guillain-Barré syndrome." (PMID 39835139, 2024).
rheumatoid arthritis (continued). "HLA-DRB1 was previously reported by GWAS to be associated with asthma, rheumatoid arthritis and systemic lupus erythematosus, implying its potential role in immune system modulation and it could thus be a candidate modifier of the disease." (PMID 36967753, 2023). "On the other hand, HLA gene polymorphisms might destroy the autoimmune state, such as HLA-DQ2 and HLA-DQ8 related with celiac diseases, HLA-DRB1 related with rheumatoid arthritis, and HLA-b27 associated with spondyloarthritis." (PMID 37691828, 2023). "Association of HLA-DRB1*04:01 with rheumatoid nodules is classical." (PMID 34248985, 2021). "In addition, miR-499 regulates class II human leukocytic antigen (HLA-II), including HLA-DRB1, which is significantly associated with rheumatoid arthritis (RA), an autoimmune disease characterized by substantial chronic inflammatory condition." (PMID 34576267, 2021). "Similarly, although related to auto-immunity, three amino acid variants located in the binding groove of the HLA-DRB1 locus are known to mediate disease association in rheumatoid arthritis." (PMID 33803005, 2021). "HLA-DRB1*04:01 was weakly associated with rheumatoid nodules." (PMID 34248985, 2021). "Studies by Linn-Rasker, Verpoort, Michou et al9,11,20 have investigated the association between genes and tobacco smoking in rheumatoid arthritis patients and suggested a tendency towards an interaction between the HLA-DRB1*0401 allele and smoking behaviour for anti-CCP positivity." (PMID 32515416, 2020). "Identifying relationships between HLA-DRB1 alleles and rheumatoid arthritis is important for identifying disease associations in different ethnic groups in order to reach a better understanding of rheumatoid arthritis worldwide." (PMID 33327594, 2020). "This widely replicated gene–environment interaction has allowed insight into the aetiology of rheumatoid arthritis—smoking increases risk by causing citrullination of proteins, which are better able to activate the immune response in the presence of HLA-DRB1 shared epitope." (PMID 31731673, 2019). "Similarly, carriage of the shared epitope, comprising HLA-DRB1*04, interacts with smoking to increase the risk of rheumatoid arthritis." (PMID 28597127, 2017). "Interestingly, the HLA-DRB1*04:01 allele has been associated with an increased occurrence of rheumatoid arthritis in the Caucasian population." (PMID 28057002, 2017). "The HLA-DRB1*04 gene are associated with Rheumatoid arthritis (RA)." (PMID 26901036, 2016). "In addition, African Americans positive for ‘HLA-DRB1 shared epitope’ alleles have a higher risk of developing rheumatoid arthritis when they demonstrate a higher degree of European ancestry, which demonstrates genetic admixture." (PMID 26817483, 2016). "Finally, 22 studies performed on the association of HLA-DRB1 with rheumatoid arthritis in Chinese populations were included and analyzed." (PMID 24161032, 2013). "We aimed to investigate GSTM1 CNV in Rheumatoid Arthritis (RA) in relation to smoking and HLA-DRB1 shared epitope; the two best known risk factors for RA and in addition, to perform subanalyses in patients where relations between variations in GSTM1 and RA have previously been described." (PMID 21445357, 2011). "The HLA-DRB1 gene on chromosome 6 has been linked to rheumatoid arthritis." (PMID 20018056, 2009). "The association between HLA-DRB1 gene and rheumatoid arthritis is very strong." (PMID 20018001, 2009). "The region near the HLA-DRB1 gene, in addition, presents an unusual context for rheumatoid arthritis (RA), on account of the very strong effect of certain HLA-DRB1 alleles on the phenotype, potentially inducing deviation from Hardy-Weinberg equilibrium (dHWE) in nearby SNPs in case-control samples." (PMID 18466524, 2007). "HLA-DRB1*04 homozygosity is associated with severe extra-articular disease in rheumatoid arthritis (RA)." (PMID 39941587, 2025).
rheumatoid arthritis (continued). "Rheumatoid arthritis (RA) is an autoimmune disease influenced by genetic factors, particularly HLA-DRB1 alleles." (PMID 40433380, 2025). "CD4+ T cell autoreactivity against citrullinated (cit) self-epitopes presented by HLA-DRB1 is associated with rheumatoid arthritis (RA) pathogenesis." (PMID 40466907, 2025). "Anti-citrullinated protein/peptide antibodies (ACPA) are crucial for the diagnosis and prognosis of rheumatoid arthritis (RA) and are associated with class II HLA-DRB1 alleles." (PMID 38765443, 2024). "Rheumatoid arthritis (RA) development is closely associated with the expression of HLA-DRB1*04:01, *04:05, *04:08, *14:02, and *10:01; similar HLA molecules:antigenic groove of these protein alleles shows the shared Q(K/R)RAA motif." (PMID 39200390, 2024). "We provide an application case by examining three Spike protein-derived immunodominant CD4+ T-cell epitopes restricted by HLA-DRB1*04:01, an allele strongly associated with susceptibility to rheumatoid arthritis (RA)." (PMID 38840924, 2024). "HLA-DRB1 shared epitope risk alleles are the strongest genetic risk factors for rheumatoid arthritis (RA) and potential biomarkers for treatment response to biological disease-modifying antirheumatic drugs (bDMARDs)." (PMID 37709837, 2023). "In rheumatoid arthritis (RA) the cusp region that is coded by disease-associated HLA-DRB1 alleles encompasses a ‘shared epitope’ (SE), which has been shown to act as a ligand that activates in vitro and in vivo pro-arthritogenic events in mice." (PMID 35902632, 2022). "HLA-DRB1 haplotypes associated with susceptibility to rheumatoid arthritis (RA) consistently show the same magnitude and direction of association for overall and CV mortality in IP." (PMID 35468805, 2022). "HLA-DRB1/DRB5 rs660895*G allele is associated with increased risk of rheumatoid arthritis (RA) in Europeans and Asians, IgA nephropathy in Asians, while the decreased risk of ulcerative colitis and inflammatory bowel disease (IBD)." (PMID 33517400, 2021). "For anti-citrullinated protein antibody positive rheumatoid arthritis (RA), HLA-DRB1 shared epitope (SE) alleles are the major genetic risk factors." (PMID 34484204, 2021). "We sought to confirm our TwinsUK findings in the SCREEN-RA cohort by analysing the association between the main genetic risk factor for rheumatoid arthritis—the HLA-DRB1 shared epitope—and the gut microbiota." (PMID 33345197, 2020). "Rheumatoid arthritis (RA) is the most prevalent AD (0.5–1%), being the HLA-DRB1 is the principal locus contributing to disease susceptibility, with an estimated contribution of 30–50% to overall susceptibility to RA." (PMID 30217207, 2018). "For instance, six possible amino acid variants at position 11 in the HLA-DRB1 gene show the strongest association to rheumatoid arthritis (RA)." (PMID 28449694, 2017). "The HLA-DRB1 locus is associated with rheumatoid arthritis (RA) in most racial groups and accounts for approximately one-third of the genetic susceptibility to RA." (PMID 28481943, 2017). "Antibodies to citrullinated proteins, common in rheumatoid arthritis (RA) patients, are strongly associated to a specific set of HLA-DR alleles including HLA-DRB1*04:01, *04:04, and *01:01." (PMID 27895642, 2016). "Susceptibility to rheumatoid arthritis (RA) is associated with defined HLA-DRB1 alleles that are related to expression, and there is thought to be a negative correlation between incidences of RA and schizophrenia." (PMID 26998349, 2016). "Other studies on candidate genes have shown that genetic variants of human leukocyte antigen (HLA)-DRB1, which mainly causes osteoarthritis (OA) and rheumatoid arthritis (RA), were also associated with KBD." (PMID 24776925, 2014). "For instance, HLA-DRB1 alleles affording susceptibility to Rheumatoid arthritis (RA) share a conserved sequence of amino acids at residues 67–74 of the DRβ chain, which is situated on one of the alpha helices flanking the peptide-binding groove." (PMID 24133494, 2013).
rheumatoid arthritis (continued). "Susceptibility for developing rheumatoid arthritis (RA) is associated with particular HLA-DRB1 alleles like HLA-DRB1*04, HLA-DRB1*01 and HLA-DRB1*10." (PMID 23737967, 2013). "This study was performed to systematically summarize results on the association of HLA-DRB1 with rheumatoid arthritis (RA) in China." (PMID 24161032, 2013). "HLA-DRB1 shared epitope (SE) alleles are the strongest genetic determinants for autoantibody positive rheumatoid arthritis (RA)." (PMID 22461888, 2012). "The strongest known genetic association with rheumatoid arthritis (RA) is the HLA-DRB1 locus, which is part of the major histocompatibility complex on chromosome 6." (PMID 20018077, 2009). "In this paper, we conduct genome-wide searches for RA-associated gene-gene interactions that involve PTPN22 or HLA-DRB1 using the Genetic Analysis Workshop 16 Problem 1 data from the North American Rheumatoid Arthritis Consortium." (PMID 20017999, 2009). "The HLA locus, and in particular several alleles of HLA-DRB1, have been associated with rheumatoid arthritis (RA) and other autoimmune disorders." (PMID 18466483, 2007). "Association between HLA-B*44, HLA-DRB1*04 and HLA-A*03 alleles and different RF and anti-CCP levels in patients with seropositive rheumatoid arthritis (multinomial logistic regression)." (PMID 41325321, 2025). "Another gene–gene interaction of importance is between HLA-DRB1 and PTPN2, which are both key susceptibility genes in anti-CCP–positive rheumatoid arthritis (anti-CCP + RA)." (PMID 41026325, 2025). "Increased susceptibility has been linked to HLA-DRB1 and HLA-DR4 alleles, as well as to autoimmune conditions including Graves’ disease, type 1 diabetes, rheumatoid arthritis, and autoimmune thyroid disease." (PMID 41523385, 2025). "Genetic studies showed that HLA-DRB1 alleles (HLA-DRB1*04, *01, and *10) have been linked to an increased chance of developing rheumatoid arthritis." (PMID 38827788, 2024). "For example, the interaction between HLA-DRB1 and miR-3928 was established in inflammatory diseases such as rheumatoid arthritis." (PMID 39126112, 2024). "For instance, several HLA-DRB1 alleles have been associated with susceptibility to rheumatoid arthritis (RA) in different populations, HLA-DQA1 and HLA-DQB1 alleles have been strongly associated with type-1 diabetes and celiac disease, and specific HLA-DRB3*03:01 allele with Crohn’s disease." (PMID 39835139, 2024). "In conclusion, our data suggested that HLA-DRB1 genetic polymorphism affects the expression of anti-cyclic citrullinated peptide (anti-CCP) and rheumatoid factor (RF) in rheumatoid arthritis (RA) patients." (PMID 37569411, 2023). "HLA-DRB1 was expressed in 90% of cases with Felty’s syndrome as well as in patients with T-LGL leukemia in the wake of rheumatoid arthritis." (PMID 37920595, 2023). "In particular, the HLA DRB1*01 and HLADRB1 * 04 antigens contain five amino acids in the antigen presentation area which are closely related to the onset of rheumatoid arthritis." (PMID 36136068, 2022). "Among the gained nonsense MNVs, one of the affected genes was HLA-DRB1, which is related to rheumatoid arthritis." (PMID 35156024, 2022). "In a small percentage of patients, a condition that resembles rheumatoid arthritis (RA) may develop, possibly caused by the presence of the HLA-DRB1 gene (associated with the development of RA) in these patients." (PMID 35260197, 2022). "Our main finding is the association of antibodies to the epitope borne by the citrullinated peptide α501–515 on the alpha chain of fibrin, with HLA-DRB1*04:01 and with rheumatoid nodules." (PMID 34248985, 2021). "The aim of this study was to compare the clinical effectiveness of tofacitinib and abatacept and clarify the impact of the HLA-DRB1 shared epitope (SE) on responses to these treatments in patients with rheumatoid arthritis (RA)." (PMID 34465391, 2021).